MST1R (macrophage stimulating 1 receptor)
Diseases named in the same sentence as MST1R in open-access papers (continued):
Sharing a sentence is not in itself a finding about the gene and the disease.
tumor (continued). "Importantly, number of genes responsible tumor immune responses and desmoplastic reaction; Mst1r, TGFβr1, TGFβr2, VEGFa, CSF-1, SDF-2, CD44, IL-6ra, PD1, CD68, CD163, fibronection and MMPs were significantly reduced." (PMID 26429877, 2015). "Similarly, the signaling initiated by the binding of MST1 to its receptor (MST1R) is an important pathway for invasive growth in different neoplasias." (PMID 26097883, 2015). "The named integrins also interact with tyrosine kinase receptors (e.g., EGFR-ERBB2, MST1R/macrophage stimulating 1 receptor, and c-MET/methoprene-tolerant) and their ligands, helping to amplify the oncogenic signaling in tumor cells." (PMID 39329988, 2024). "Another research indicated that the four novel tumor suppressor candidates including GPR180, MST1R, OCIAD2, and PARP6 were potentially useful molecular markers for predicting poor prognosis in HB patients." (PMID 33312943, 2020). "Whether other kinases, such as MST1R, ERBB3, etc., have an impact on the anti-tumor effect of oncolytic viruses remains to be further studied by other members of the team." (PMID 35401439, 2022). "The highest frequency of chromosome 3p deletion, locus of MST1R and BAP1, indicated that the inactivation of tumor suppressor genes in this chromosome might be an early event contributing to transformation from nasopharyngeal epithelium to NPC." (PMID 34031426, 2021).
infection (5 papers, 2022 to 2025). The state of being infected such as from the introduction of a foreign agent such as serum, vaccine, antigenic substance or organism. "Flow cytometry results show that siRNA silencing the expression of SGK3, ULK3, ERBB4, STK17B can reduce the infection efficiency of ORFV-GFP virus, while siRNA silencing the expression of MST1R, PAK4, ERBB3 can increase the infection of ORFV-GFP virus efficient." (PMID 35401439, 2022).
psychiatric disorder (2 papers, 2024 to 2025). A disorder characterized by behavioral and/or psychological abnormalities, often accompanied by physical symptoms. "In line with our study, MST1R and RF123 are considered to be associated with brain function or psychiatric disorders, exhibiting upregulated expression in various brain regions." (PMID 38425786, 2024).
MST1R also shares sentences with these, for which no sentence is quoted: endometriosis (3 papers); scoliosis (3); adenocarcinoma (2); bladder tumor (2); endotoxemia (2); head and neck cancer (2); Lady Windermere syndrome (2); metastatic disease (2); adenoma (1); atherosclerosis (1); bacterial infection (1); bladder papilloma (1); brain tumors (1); cervical cancer (1); chordoma (1); co-infection (1); colitis (1); colon adenocarcinoma (1); colon cancer (1); esophageal cancer (1); Ewing sarcoma (1); experimental autoimmune encephalomyelitis (1); gastric adenocarcinoma (1); head–neck squamous cell carcinoma (1); immune disease (1); Insulin resistance (1); intraepithelial neoplasia (1); leukemia (1); lung adenocarcinoma (1); lymph node metastasis (1).
A further 18 diseases each share a sentence with MST1R in 1 paper.